RNF126 (ring finger protein 126)
Diseases named in the same sentence as RNF126 in open-access papers (continued):
Sharing a sentence is not in itself a finding about the gene and the disease.
asthma (1 paper, 2022). "Although the effect of RNF126 on asthma has not been previously reported, it is confirmed that RNF126 plays an oncogene role in a variety of cancers." (PMID 36393974, 2022). "The study reveals that the potential molecular pathways for asthma include FOXC1-miR-PI3K/AKT, which indicates that RNF126 and PI3K/AKT pathways may have therapeutic effect in asthma." (PMID 36393974, 2022).
breast tumors (1 paper, 2023). "First, we used the Cre‐PyMT virus to induce breast tumors in Rnf126fl/fl or Rnf126 wild‐type FVB mice." (PMID 36563124, 2023).
cardiac hypertrophy (1 paper, 2022). "Additionally, ANG II activated ERK/glycogen-synthase kinase-3 (GSK3), phosphorylated heat shock transcription factor 1 (HSF1), resulting in a protein-coding gene RNF126 (ring finger protein 126) degradation for stabilizing IGF-IIR protein expression and leading to cardiac hypertrophy." (PMID 36359731, 2022).
emphysema (1 paper, 2021). "The cytosolic transport (RNF126, PLEKHJ1, VPS51, and AP1G1), target of rapamycin (mTOR) signaling (PIK3CA, STK11, RPS6KB2, and PRR5), regulation of translation, metabolic regulation, and apoptosis are involved in the percent emphysema-associated network." (PMID 34777474, 2021).
Friedreich ataxia (1 paper, 2017). An inherited condition that affects the nervous system and causes movement problems. "Depletion of RNF126 in cells derived from FRDA patients promotes accumulation of mature frataxin, pointing toward this E3 ligase as a new potential therapeutic target for Friedreich ataxia." (PMID 28228265, 2017). "Most importantly, RNF126 depletion results in frataxin accumulation in cells derived from FRDA patients, highlighting the relevance of RNF126 as a new therapeutic target for Friedreich ataxia." (PMID 28228265, 2017).
glioma (1 paper, 2020). A benign or malignant brain and spinal cord tumor that arises from glial cells (astrocytes, oligodendrocytes, ependymal cells). "Loss of p27 or CKI-1B promotes cell cycle progression and glioma cell proliferation, whereas shRNA-mediated silencing of RNF126 reverses these phenotypes." (PMID 32984016, 2020). "RNF126 is overexpressed in glioma tissues, degrading p27, which promotes the growth of glioma cells." (PMID 32984016, 2020).
Gordon Holmes syndrome (1 paper, 2023). "Mutations in RNF126 and RNF12 cause Gordon Holmes syndrome and X-linked intellectual disability, respectively." (PMID 37667177, 2023).
hepatocellular carcinoma (1 paper, 2025). A malignant tumor that arises from hepatocytes. "Additionally, by ubiquitinating and degrading liver kinase B1 (LKB1), RNF126 destabilizes this protein, promoting stem-like characteristics, migration, and angiogenesis in hepatocellular carcinoma (HCC)." (PMID 40410177, 2025).
Infertility (1 paper, 2025). "Targeting Rnf126 results in different types of germ cells reduction, infertility, and microtubule-associated motor activity failure (MMAF), characterized by spermatozoa with truncated, twisted, and malformed flagella." (PMID 40410177, 2025).
leukemia (1 paper, 2020). A malignant (clonal) hematologic disorder, involving hematopoietic stem cells and characterized by the presence of primitive or atypical myeloid or lymphoid cells in the bone marrow and the blood. "This relationship between NTS-induced mTOR downregulation and RNF126 upregulation was observed in several leukemia cell lines." (PMID 32131492, 2020). "We then examined RNF126 expression levels in several cancer cell lines and found RNF126 expression levels were reduced, including in leukemia cell lines." (PMID 32131492, 2020). "Of particular note, we identified RNF126 as a novel E3 ligase for mTOR in NTS-treated leukemia cells." (PMID 32131492, 2020). "RNF126 strongly induced mTOR ubiquitination in both wild type and K48 ubiquitin-overexpressing leukemia cells." (PMID 32131492, 2020). "We found RNF126 could induce cytotoxicity in leukemia cells in an E3 ligase-dependent manner and cell-cycle analysis showed G2/M phase arrest in RNF126 overexpressing leukemia cells." (PMID 32131492, 2020). "This may explain the observation that NTS-induced leukemia cell death was inhibited in RNF126 knock-down cells." (PMID 32131492, 2020). "In addition, our study offers strong evidence that RNF126 is a novel tumor-suppressive E3 ligase that regulates mTOR in leukemia cells." (PMID 32131492, 2020). "mTOR was downregulated in RNF126-overexpressing leukemia cells." (PMID 32131492, 2020). "However, the role of RNF126 in leukemia development is still unclear." (PMID 32131492, 2020). "However, RNF126 was found to induce the downregulation of mTOR in leukemia cells." (PMID 32131492, 2020). "Using NTS or targeting RNF126 could be a beneficial therapeutic approach for leukemia therapy." (PMID 32131492, 2020). "If NTS could regulate MUL1 or RNF126 activity at the same time, NTS will be a strong therapeutic tool for leukemia therapy compared to other drugs (e.g., Imatinib) through AKT or mTOR ubiquitination." (PMID 32131492, 2020). "ROS inhibition prevented RNF126 expression and mTOR ubiquitination in NTS-treated leukemia cells." (PMID 32131492, 2020).
lung adenocarcinoma (1 paper, 2016). A carcinoma that arises from the lung and is characterized by the presence of malignant glandular epithelial cells. "Next, we investigated the importance of the RING-like domain of RNF126 on the destabilization of endogenous PDK1 in human lung adenocarcinoma PC8 cells." (PMID 27462466, 2016).
male infertility (1 paper, 2025). The inability of the male to effect fertilization of an ovum after a specified period of unprotected intercourse. "Our research suggests that Rnf126 defects may serve as both a pathogenic factor and a diagnostic marker for male infertility in cases of asthenoteratozoospermia." (PMID 40410177, 2025). "In this investigation, we identified a deleterious variation of Rnf126 that results in male infertility and asthenoteratozoospermia." (PMID 40410177, 2025). "Understanding the functional role of RNF126 not only deepens insights into the fundamental biology of male reproduction but also holds significant translational potential for addressing idiopathic male infertility and enhancing the efficacy of assisted reproductive technologies." (PMID 40410177, 2025). "Investigating Rnf126 function in spermatogenesis, together with empirical findings on MMAF presentation, may improve our understanding of the developmental processes involved in sperm flagellum formation and contribute to elucidating the causes of male infertility." (PMID 40410177, 2025).
mucinous ovarian cancer (1 paper, 2025). An invasive malignant neoplasm that arises from the ovary and is characterized by the presence of malignant epithelial cells that contain intracytoplasmic mucin and may resemble the epithelial cells of the endocervix or gastrointestinal tract. "To determine the function of RNF126 in OC cells, we first established control and RNF126-depleted human serous ovarian cancer SKOV3 cells and mucinous ovarian cancer MCAS cells using the CRISPR/Cas9 system." (PMID 41465608, 2025).
oligoasthenoteratozoospermia (1 paper, 2025). A form of male infertility that is characterized by a combination of low number or oligozoospermia, poor motility or asthenozoospermia, and abnormal shape or teratozoospermia of sperms. "RNA sequencing revealed that sperm samples from oligoasthenoteratozoospermia (OAT) patients exhibited significantly lower RNF126 expression levels compared to those from normozoospermic individuals." (PMID 40410177, 2025).
papillary carcinoma (1 paper, 2021). A malignant epithelial neoplasm characterized by a papillary growth pattern. "Furthermore, the transcription level of RNF126 in papillary carcinoma is higher than that in non-papillary carcinoma." (PMID 33664240, 2021).
testicular germ cell tumor (1 paper, 2026). A germ cell tumor arising from the testis.
triple-negative breast carcinoma (1 paper, 2025). An invasive breast carcinoma which is negative for expression of estrogen receptor (ER), progesterone receptor (PR), and human epidermal growth factor receptor 2 (HER2). "For example, the E3 ligase RNF126 ubiquitinates MRE11, thereby activating the DNA damage response in triple-negative breast cancer and contributing to resistance to radiotherapy." (PMID 40697329, 2025).
cancer (18 papers, 2014 to 2025). A tumor composed of atypical neoplastic, often pleomorphic cells that invade other tissues. "E3 ubiquitin ligase RNF126 (ring finger protein 126) is highly expressed in various cancers and strongly associated with tumorigenesis." (PMID 33664240, 2021). "RNF126 expression has been shown to be suppressed in several cancer cell lines, and low expression of RNF126 was associated with poor survival of cancer patients in the TCGA database." (PMID 32131492, 2020). "Despite numerous conflicting reports concerning the biological function of RNF126 in cancer, our results indicate that RNF126 is associated with NTS-induced antileukemia effects via mTOR downregulation." (PMID 32131492, 2020). "RNF126 has been implicated in a number of physiological and pathological processes, such as cancer progression, membrane receptor trafficking, and immune response modulation." (PMID 28228265, 2017). "Thus, we suspect that Rnf126 KO mice harbor more genome instability and increased cancer susceptibility." (PMID 36563124, 2023). "Low expression of RNF126 was shown to be associated with poor survival in several cancer patients." (PMID 32131492, 2020). "Secondly, RNF126 may represent a novel therapeutic target for treating cancer by targeting K48-linked ubiquitination of mTOR." (PMID 32131492, 2020). "Indeed, various cancers listed in The Cancer Genome Atlas reportedly harbor single or combinatorial RNF126 alterations, including mutations, deletions, or amplifications." (PMID 30529286, 2018). "Studies have shown that inhibition of RNF126 suppresses cancer cell proliferation, and the elucidation of its function has provided researchers with details for developing a potential treatment strategy." (PMID 37760968, 2023). "RNF126 (ring finger protein 126), acting as a E3 ubiquitin ligase, has been reported to be overexpressed in numerous cancer types and correlated with tumorigenesis." (PMID 37215134, 2023). "In TNBC, depletion of RNF126 increased sensitivity to irradiation, providing evidence for a possible treatment prospect for a type of cancer that is difficult to treat." (PMID 37760968, 2023). "The E3 ligase RNF126 has been found to target PDK1 for proteasomal degradation to promote cancer cell progression." (PMID 35006464, 2021). "The RING type E3 ligases RNF126 and breast cancer associated gene 2 (BCA2) both play important roles in DNA damage repair and cancer development." (PMID 35006464, 2021). "Taken together, these data indicated that ERK phosphorylation and RNF126 are lost under the detached condition in normal cells, but are maintained in most cancer cells." (PMID 27462466, 2016). "As anoikis resistance is important for tumorigenic activity of cancer cells in vivo, we assessed the effect of RNF126 on tumor formation." (PMID 27462466, 2016). "U0126 treatment decreased RNF126 levels in detached cancer cells, except in BT-474 and MDA-MB-453 cells, where U0126 treatment did not affect RNF126 levels." (PMID 27462466, 2016). "In this study, we revealed the molecular mechanism of RNF126 on anchorage-independent cancer growth and OXPHOS regulation." (PMID 27462466, 2016). "All of the cancer cell lines (except for BT-474 cells) expressed RNF126 at higher levels than did MCF-10A cells in the attached state." (PMID 27462466, 2016). "When cells were cultured in the detached state, RNF126 depletion increased the percentage of trypan blue-positive cells, indicating that RNF126 is necessary for cancer cells to survive in the detached state." (PMID 27462466, 2016). "RNF126 expression in cancer cells was found to be under the control of the extracellular signal-regulated kinase signaling pathway, which is essential for anoikis resistance." (PMID 27462466, 2016). "Recent evidence suggested a role for the RNF126 E3 ubiquitin ligase in promoting cancer cell proliferation by p21 degradation." (PMID 25121590, 2014). "RNF126 is upregulated in several cancer types and is essential for their proliferation." (PMID 40086734, 2025).
cancer (continued). "RNF126 targets many proteins for ubiquitination and is involved in various biological processes, such as male fertility, quality control of misfolded proteins, energy metabolism, and cancer progression." (PMID 41465608, 2025). "The third approach includes inhibiting enzymatic function, blocking PPI or other mechanisms, which might be the desired mechanism for cancer therapy when considering the role of RNF126, RNF168, and CUL1." (PMID 37760968, 2023). "This may seem contrary to the previous claims that RNF126 could be a potential target protein for cancer therapy." (PMID 37760968, 2023). "Because RNF126 depletion attenuates tumorigenicity and colony-forming ability in soft agar, the maintained expression of RNF126 in the detached state appears to be important for tumorigenicity in cancer cells." (PMID 27462466, 2016). "Thus, RNF126 is an attractive molecule for treating cancer by selectively targeting anchorage-independent growth." (PMID 27462466, 2016). "Although excess expression of RNF126 decreased the tumorigenicity in MDA-MB-231 cells, RNF126 expression at appropriate levels in the tumor microenvironment might worsen the prognosis of cancer patients." (PMID 27462466, 2016). "Thus, RNF126 was identified here as a new regulator of anchorage-independent growth for cancer cells and therefore is a potential target for developing novel cancer therapeutics." (PMID 27462466, 2016). "Moreover, depletion of RNF126 or increased expression of PDK1 in cancer cells suppressed colony formation in soft agar as well as tumorigenicity in mice." (PMID 27462466, 2016). "The upregulation of RNF126 in these cells coincides with an increase in mitochondrial biogenesis, suggesting that the RNF126-mediated quality control mechanism described here may contribute to the rapid propagation of these cancer cells." (PMID 40086734, 2025). "Thus, RNF126 has a key role in anoikis resistance in cancer cells." (PMID 27462466, 2016). "Thus, RNF126 depletion may diminish tumorigenicity of cells mainly by affecting the fine-tuning of PDK1 activity in cancer cells." (PMID 27462466, 2016). "Then, we examined whether RNF126 has a role in anoikis resistance in cancer cells." (PMID 27462466, 2016). "This section discusses ubiquitin pathway-targeting drugs and some of the strategies for the development as well as the potential utilization of RNF126, RNF168 and the CUL1 and SCF complex and its related factors for cancer therapy and diagnostics." (PMID 37760968, 2023). "RNF126, RNF168 and CUL1 are involved in DNA damage response (DDR), DNA double-strand break (DSB) repair, cell cycle regulation, and ultimately, cancer cell proliferation control." (PMID 37760968, 2023). "RNF168, RNF126, and CUL1 are involved in several cellular functions which are critical for the hallmarks of cancer." (PMID 37760968, 2023). "Therefore, RNF126 may be a key factor in ERK signaling-mediated anoikis resistance in cancer cells." (PMID 27462466, 2016). "RNF126 negatively regulated PDK protein levels and was necessary for the tumorigenicity of cancer cells in mice." (PMID 27462466, 2016). "In contrast, most cancer cells showed maintained or increased phosphorylated ERK and RNF126 levels under the detached condition." (PMID 27462466, 2016). "Moreover, RNF126 showed a positive correlation with both RelA and AKT at the mRNA level in most cancer and normal tissues through correlation analysis of The Cancer Genome Atlas (TCGA) database and The Genotype‐Tissue Expression (GTEx) database, respectively." (PMID 36563124, 2023). "Since both of RNF126 and BCA2 could regulate DNA damage repair and cancer development, they may be the promising targets for cancer therapy." (PMID 35006464, 2021). "A paper indicates a role for RNF126 in promoting resistance to anoikis by degrading pyruvate dehydrogenase kinase (PDK) and allowing increased flux toward tricarboxylic acid (TCA) cycle, thus conferring metastatic ability on cancer cells." (PMID 28228265, 2017).
cancer (continued). "Combined with the previous reported similar results, we concluded that RNF126 nonspecifically regulated the growth of cancer cells." (PMID 27227488, 2016). "Here we report the pivotal role of an E3 ubiquitin ligase, ring-finger protein 126 (RNF126), in the resistance of cancer cells to the stress associated with non-adherent conditions." (PMID 27462466, 2016).